BDNF (brain derived neurotrophic factor)
Diseases named in the same sentence as BDNF in open-access papers (continued):
Sharing a sentence is not in itself a finding about the gene and the disease.
depression (continued). "Depression has been linked with psychomotor disengagement, oxidative stress burden and decreased blood levels of brain-derived neurotrophic factor (BDNF)." (PMID 36295524, 2022). "The results regarding the effect on depressive symptoms have been inconsistent, indicating that there are still factors to be examined that moderate the influence of BDNF on the risk of depression." (PMID 35886019, 2022). "This is intriguing because previous studies have reported the potential implications of Rai14 in the BDNF and mTOR pathways, which are critical processes for depression-associated synaptic remodeling." (PMID 35467532, 2022). "Meta-analysis pooling of gene association studies of human subjects with the Val66Met BDNF SNP showed an association with depression in late life only." (PMID 35909451, 2022). "It was found that 5-HT stimulates BDNF expression while BDNF promotes the neurogenesis and neuronal survival of 5-HT; impairment in this mechanism is claimed to cause depression symptoms." (PMID 36078738, 2022). "It is noteworthy that BDNF expression was associated with the neurotrophic theory of depression etiology." (PMID 36355545, 2022). "One of the role of plasmin is to convert pro-BDNF into mature BDNF in the brain, and thus this pathway has been implicated in depression and treatment response." (PMID 36386166, 2022). "Current research has identified associations between changes in serum BDNF levels and post-stroke depression." (PMID 36142325, 2022). "It is generally recognized that depression is associated with an imbalance in the impairment of BDNF and certain neurotransmitters such as 5-HT, DA, GLU, and NE in the central nervous system." (PMID 35237160, 2022). "Since BDNF has been implicated in the anti-depression effects and improvement in memory produced by several drugs, we evaluated the effects of CUR on BDNF in the frontal cortex and hippocampus of TB mice." (PMID 35216083, 2022). "IBS is associated with a high risk of comorbid depression, and recent studies have evaluated the role of BDNF in IBS." (PMID 36499295, 2022). "The main aim of this study was to determine the potential role of the BDNF Val66Met polymorphism in the relationship between depression and physical activity in a large sample of community-based adults." (PMID 35206257, 2022). "Another CNS important molecule associated with resilience and depression mood, the brain-derived neurotrophic factor (BDNF) promotes the survival of neurons by playing a role in the growth, maturation and maintenance of these cells." (PMID 36386785, 2022). "Low levels of BDNF are linked to cognitive decline and depression, with circulating levels increased by physical exercise." (PMID 35832286, 2022). "While chronic alternations of BDNF expression (most commonly downregulation) are associated with psychopathologies, including depression and anxiety, the response of BDNF to an acute stress remains elusive, and so is its role in thermoregulation." (PMID 35456946, 2022). "In patients with high working memory, higher baseline BDNF was associated with lower levels of depression after treatment." (PMID 36672535, 2022). "Further to this, other mechanisms proposed include the relationship between EEG alpha power and brain-derived neurotrophic factor (BDNF) Met/Met polymorphism, an indicator of depression severity." (PMID 36713924, 2022). "The relationship between depression and the Val66Met polymorphism at the brain-derived neurotrophic factor gene (BDNF), has been largely studied." (PMID 35206257, 2022). "Previous data showed that factors such as structural changes within the hippocampus, loss of BDNF, and excessive neuroinflammation are important in the development of depression." (PMID 35496273, 2022). "Brain-derived neurotrophic factor (BDNF) is another important factor to regulate the synaptic structure of hippocampal neurons in stress caused depression." (PMID 34984950, 2022).
depression (continued). "Associations among circulating BDNF, depression and EV-derived miRNAs related to atherothrombosis have been evaluated in a large Italian cohort of obese individuals (n = 743), characterized by the Beck Depression Inventory (BDI-II) score." (PMID 35911513, 2022). "The potential association between depression and cardiovascular illness and brain-derived neurotrophic factor (BDNF) has also been confirmed by recent research." (PMID 36532555, 2022). "The reduction of BDNF levels is associated with chronic psychiatric and neurological disorders, including anxiety and depression." (PMID 35646186, 2022). "Several studies have also reported significant associations between exercise-induce BDNF upregulation and improved cognition and depression symptoms." (PMID 36233029, 2022). "BDNF is a downstream target of CREB, and BDNF deficiency is associated with the pathophysiology of severe depression." (PMID 35668445, 2022). "Recent studies demonstrated that microglia are closely associated with depression development and BDNF can target microglia to show antidepressant effect." (PMID 36211814, 2022). "The BDNF rs6265 A allele has been considered a risk for the development of depression because allele A carriers have shown a low activity-regulated expression of BDNF and the alteration of hippocampal activation." (PMID 35886019, 2022). "This risk allele has also been associated with modifying the protein function of BDNF in humans, and although it has been extensively studied in relation to depression and physical activity, the results remain inconclusive." (PMID 35206257, 2022). "Quercetin alleviated LPS-induced depression-like behavior and impaired learning in rats caused by a BDNF-related imbalanced expression in the hippocampus and PFC." (PMID 36499295, 2022). "In conclusion, our study will provide a valuable reference for future studies on the association between depression and BDNF." (PMID 36291673, 2022). "In this study, we have already collected the documents on the association between depression and BDNF which have published in the Web of Science database." (PMID 36291673, 2022). "In both human and animal studies, altered levels of neurotrophins, particularly BDNF, and their receptors have been implicated in Major Depressive Disorder, Schizophrenia, drug addiction, Post-traumatic Stress Disorder, and other disorders." (PMID 36466807, 2022). "The association between depression and BDNF has attracted increasing academic attention over the years." (PMID 36291673, 2022). "Recent studies have indicated that BDNF is the most important representative and an attractive factor associated with depression." (PMID 36499295, 2022). "In sensitivity analyses after excluding dementia, depression, and insulin resistance-related metabolic diseases, which is closely related to BDNF, the association was maintained." (PMID 36329115, 2022). "Increases in BDNF are associated with cognitive improvement and alleviation of depression and anxiety." (PMID 35721318, 2022). "Research trends in the topic of the association between depression and BDNF showed a year-on-year over the years of retrieval." (PMID 36291673, 2022). "In line with CRTC1’s role in neuroplasticity processes, as well as the involvement of CREB and BDNF in rodent models of depression, increasing evidence suggests that CRTC1 is implicated in the pathogenesis of MDD." (PMID 35242012, 2022). "Aim of the present study was, therefore, to investigate the association among BDNF, depression and EV-derived miRNAs related to atherothrombosis in a cohort of 743 obese individuals." (PMID 35911513, 2022). "Downregulation of BDNF is associated with neuroinflammation in many brain disorders, which typically present with depression as a comorbidity." (PMID 35624812, 2022). "Recently, it has been suggested that depression is not only caused by decreased BDNF levels but also by an increase in its precursor proBDNF." (PMID 35448545, 2022).
depression (continued). "Looking at brain-derived neurotrophic factor (BDNF), a critical mediator of neuronal activity, which has been linked to depression, researchers found increased DNAm mainly in the promotor of exons I and IV in depressed patients." (PMID 35628666, 2022). "The BDNF Val66Met polymorphism has also been linked to sex differences in major depressive disorders and stress reactivity in humans." (PMID 35256586, 2022). "In this context, it is worth noting that a low level of BDNF is strongly associated with depression and antidepressant drugs can normalize BDNF levels (Castrén and Monteggia, 2021)." (PMID 36582213, 2022). "Studies have demonstrated that BDNF is a critical factor for the development and function of the 5‐HT neurotransmitter, which is a key modulatory neurotransmitter linked to anxiety and depression." (PMID 35898162, 2022). "Decreasing serum BDNF after treatment with duloxetine was associated with the improvement of the disease severity, depression, and pain level." (PMID 35501732, 2022). "BDNF is also closely associated with psychiatric disorders, and BDNF expression is downregulated in major depressive disorder (MDD) patients, and this downregulation is rescued by antidepressants." (PMID 36172354, 2022). "Both humans and mice with the BDNF val66met allele are more vulnerable to stress-induced anxiety and depression, but this is variable with age and sex." (PMID 36467104, 2022). "Neurotrophic factors, particularly BDNF, have been associated with depression and antidepressant drug action." (PMID 36142325, 2022). "The presence of frailty was significantly associated with plasma BDNF levels (odds ratio 0.508, 95% confidence interval 0.304–0.849) as well as age, hemoglobin, and the presence of dementia, and depression." (PMID 36329115, 2022). "Low plasma BDNF levels have been associated with suicidal behaviors in patients with major depression." (PMID 36316319, 2022). "An interesting point for discussion regarding the association of the rs6265 SNP of BDNF with anxiety, depression, and PTSD is that such association appears to be existent only for patients who are younger." (PMID 35528795, 2022). "Another study established that the gut microbiome dysbiosis in patients with depression is associated with decreased BDNF levels, whereas Faecalibacterium is associated with clinician depression score bars, which indicate the severity of depressive symptoms." (PMID 36499295, 2022). "Allele A of the brain-derived neurotrophic factor (BDNF) rs6265 is considered to be a risk factor for depression." (PMID 35886019, 2022). "A polymorphism in the regulatory region of the human BDNF gene, which reduces BDNF expression and release, is also associated with depression (Björkholm and Monteggia, 2016)." (PMID 36467104, 2022). "In major depressive disorder and related stress models, BDNF is associated with pro- and antidepressive-like, as well as stress susceptible and resilient, outcomes, depending on the brain region it is acting." (PMID 35722560, 2022). "A study illustrated that the alcoholic extract of sesame (Sesamum indicum L.)cake (SLE) and sesamol markedly improved CUMS-induced depression and memory loss by increasing BDNF and PSD-95 (postsynaptic density protein 95) in depressed mouse brains." (PMID 36499295, 2022). "On the other hand, BDNF is a neurotrophin that has been linked to depression in addition to having essential functions in neuroplasticity, neuronal survival, and neurogenesis." (PMID 36142808, 2022). "Elevated glucocorticoids reduce brain-derived neurotrophic factor-dependent upregulation of glutamate receptors involved in various neural circuits associated with depression and neural diseases by suppressing microRNA-132 expression." (PMID 35911274, 2022).
depression (continued). "Future research should aim to determine the possible causative role of BDNF-TrkB in the gut–brain axis in depression, which will require further animal and clinical research as well as the development of analytical approaches." (PMID 36499295, 2022). "Alterations in the expression or signalling of BDNF are implicated in the pathophysiology of mental disorders such as depression and schizophrenia, execution of motor functions and LTP and consequent memory formation." (PMID 34734461, 2022). "In depression, decreases in calcium-binding protein P11 (a 5-HT receptor-associated signaling molecule) and brain-derived neurotrophic factor (BDNF) have been demonstrated." (PMID 36013047, 2022). "Lin and colleagues studied the peripherally expressed precursor of brain-derived neurotrophic factor (proBDNF) as a pathogenic factor of depression." (PMID 35625877, 2022). "Researchers are exploring BDNF targeting via the gut–brain axis to obtain new insights regarding the pathways underlying depression." (PMID 36499295, 2022). "A persistent state of oxidative stress has been associated with both vulnerability to depression and low brain-derived neurotrophic factor (BDNF) levels." (PMID 35406124, 2022). "Until the deadline (2 August 2022), a total of 882 journals have published 5300 pieces of literature related to the association between depression and BDNF." (PMID 36291673, 2022). "BDNF is a widely studied biomarker in the nervous system and has been strongly associated with depression and Alzheimer's disease." (PMID 35699863, 2022). "A reduction of BDNF can increase anxiety and depression-like symptoms, which were also associated with depression severity and recurrence." (PMID 35281603, 2022). "This interaction suggests that the practice of physical activity exerts a dose-dependent protective effect on the risk of depression, moderated by the BDNF Val66Met genotype." (PMID 35206257, 2022). "Consistent with previous studies, we confirmed that plasma BDNF was associated with the presence of dementia and depression in this nationwide multicenter study." (PMID 36329115, 2022). "Increased BDNF levels in the hippocampus and mPFC are associated with an antidepressant-like response in behavioral models of depression, providing a biomarker that corroborates the onset of these behavioral effects." (PMID 35338110, 2022). "Contrarily, BDNF overexpression was associated with increased sucrose intake and a decrease in depression-like behavior." (PMID 36142808, 2022). "The role of hippocampal BDNF in the chicken is less understood, yet in a chick anxiety-depression model, hippocampal BDNF response was linked to stress resilience." (PMID 35729672, 2022). "We report a gene–environment interaction effect in which Met allele carriers of the BDNF Val66Met polymorphism who are more physically active showed a decreased prevalence of depression." (PMID 35206257, 2022). "Multiple studies have shown the association between the dysregulation of the BDNF signaling pathway and the development and progression of depression and cognitive decline, both of which are frequently diagnosed comorbidities in OSA patients." (PMID 36499215, 2022). "In order to reveal the research progress on the association between depression and BDNF in the time dimension, the Timezone graph supplied by CiteSpace was used to display the map of the keyword co-occurrence network." (PMID 36291673, 2022). "The development process of the research field of the association between depression and BDNF can be reflected by the change of annual output." (PMID 36291673, 2022). "BDNF is known to regulate neuronal survival and is associated with psychological dysregulation such as anxiety and depression." (PMID 36232200, 2022).
depression (continued). "GF mice exhibit markedly altered behavioural and cognitive phenotypes, in part due to altered expression of brain‐derived neurotrophic factor (BDNF) and NMDARs, implicated in depression (BDNF) and neurogenesis and synaptic plasticity (NMDARs)." (PMID 34734461, 2022). "In contrast, there is high heterogeneity in studies assessing the potential role of the BDNF Val66Met polymorphism on the effect of physical activity on depression." (PMID 35206257, 2022). "Several studies identified that decreased levels of BDNF in the context of inflammation can affect neuroplasticity and increase the susceptibility of developing depression in patients with coronary artery disease." (PMID 36078878, 2022). "Polymorphisms in the BDNF gene, among these the rs6265, have been associated with depression and acute coronary syndromes; low circulating BDNF levels have been reported in coronary artery disease and in depressed patients." (PMID 35911513, 2022). "Inflammatory factors such as interleukin (IL)-1, tumor necrosis factor (TNF)-a, nuclear factor-kappaB (NF-jB), and brain-derived neurotrophic factor (BDNF) have been implicated in the causative mechanism of depression." (PMID 35735405, 2022). "Here, we review evidence for the role of BDNF and TrkB signaling in the regions of the hypothalamus and their role in these autonomic and behavioral functions associated with depression." (PMID 36466807, 2022). "At the same time, we found that the focus of research on the association between depression and BDNF has gradually shifted from the field of “synaptic plasticity” to “oxidative stress and neuroinflammation”." (PMID 36291673, 2022). "Previous research points at a potential implication in depression and also a potential role in pain mechanisms of the BDNF Val66Met polymorphism." (PMID 35893072, 2022). "The expression pattern of above three miRNAs in AD patients caused BDNF deficiency through validated targets, and the miRNA expression trends were alleviated by education and aggregated by depression." (PMID 36040555, 2022). "Congruent to these findings, fecal microbiota transplant from IBD patients with depressive disorder contained a higher abundance of family Enterococcaceae and caused a decrease of hippocampal BDNF in transplanted mice." (PMID 36555576, 2022). "Clinical and animal studies have demonstrated that BDNF is closely associated with depression disorder." (PMID 35754496, 2022). "A mass of studies reported the association of a decrease in BDNF mRNA and protein levels in the hippocampus with an increase in susceptibility to develop depressive disorders." (PMID 35814253, 2022). "The alterations of proBDNF and mBDNF expression have been indicated in many other diseases with anxiety- and depressive-like behavior, highlighting the association between aberrant BDNF expression and anxiety and depression disorders." (PMID 35996194, 2022). "BDNF is a crucial brain signaling protein associated with depression disorder that plays a vital role in neuronal plasticity." (PMID 35873590, 2022). "BDNF is a neurotrophic factor (NF) that substantially contributes to neurogenesis in adults and is thus associated with the pathogenesis of depression." (PMID 34658847, 2021). "Further studies will be necessary in order to determine the precise mechanism underlying the relationship between reduced BDNF levels and the etiology of major depression." (PMID 34362162, 2021). "More importantly, leucine and isoleucine can increase the expression of BDNF in hippocampal neurons, and BDNF dominates the signal transduction pathways associated with depression." (PMID 34557088, 2021). "Brain-derived neurotrophic factor (BDNF) is associated with many neuropsychiatric diseases, including alcohol use disorders and depression." (PMID 34526917, 2021). "SD was also found to increase BDNF levels in patients with major depressive disorder, and severe insomnia has been associated to lower BDNF." (PMID 34207633, 2021).